WWOX (WW domain containing oxidoreductase)
Diseases named in the same sentence as WWOX in open-access papers (continued):
Sharing a sentence is not in itself a finding about the gene and the disease.
Ataxia (15 papers, 2015 to 2024). Ataxia refers to impaired coordination of voluntary muscle movement. "WWOX encodes for a short-chain oxidoreductase and is mutated in cerebellar ataxia and microcephaly syndrome patients with intellectual disability." (PMID 39365306, 2024). "Null mutations of WWOX/Wwox gene cause severe neural diseases (e.g. epilepsy, microcephaly, retinal degeneration, and ataxia), metabolic disorders (including lipid, cholesterol and glucose metabolism), and early death in the newborns." (PMID 31315632, 2019). "The observed higher WWOX expression in cerebellum and in specific cell types, such as basket cells and granule cells, is undoubtedly related to the observation that cerebellar ataxia is a syndromic condition associated with WWOX loss of function both in humans and rodent models." (PMID 33255508, 2020). "Null mutations of WWOX/Wwox gene cause severe neural diseases (e.g., epileptic encephalopathy, microcephaly, and spinocerebellar ataxia), metabolic disorders (including lipid, cholesterol, and glucose metabolism), disorder of sex differentiation, and early death in the newborns." (PMID 31123603, 2019). "Notably, null mutations of WWOX/Wwox gene in humans, rats and mice result in severe neural diseases (e.g. microcephaly, seizure, ataxia, etc.), growth retardation, metabolic disorders, and significantly shortening of life span." (PMID 27845895, 2017). "In a recent study, we reported that conditional ablation of WWOX in neurons phenocopies the Wwox‐null mice including growth retardation, spontaneous epileptic seizures, ataxia, and premature death at 3–4 weeks." (PMID 34747138, 2021). "WWOX missense mutations lead to hypomorphic alleles related to SCAR12 syndrome, an early-childhood onset cerebellar ataxia associated with non-progressive microcephaly, generalized tonic-clonic epilepsy, and developmental delay." (PMID 35573960, 2022).
Epileptic encephalopathy (15 papers, 2015 to 2026). A condition in which epileptiform abnormalities are believed to contribute to the progressive disturbance in cerebral function. "Biallelic pathogenic variants of WWOX, represented by homozygous and compound heterozygous variants, have been associated with an early infantile epileptic encephalopathy known as WOREE syndrome (MIM: 616211)." (PMID 38161429, 2023). "Several studies identified MRI features related to WWOX gene mutations in children with epileptic encephalopathy and we will try to put together all the characteristics described to date, to define a unique radiological pattern." (PMID 38161429, 2023). "Overall, our data demonstrate the ability of brain organoids to model childhood epileptic encephalopathies, while elucidating the pathological changes seen in patients with germline mutations of WWOX and possible approaches for treatment development." (PMID 34268881, 2021). "In conclusion, germline pathogenic variants in WWOX are clearly associated with a severeearly-onset epileptic encephalopathy called WOREE syndrome and we report here onthe largest cohort of individuals with this neurological disorder." (PMID 30356099, 2019). "This study identifies two siblings with novel WWOX gene mutation who presented for evaluation of epileptic encephalopathy." (PMID 27495153, 2016). "The study presents the importance of human WWOX gene for brain development and the association between gene mutation and epileptic encephalopathy." (PMID 27495153, 2016). "Moreover, this case confirms the involvement of WWOX in the pathogenesis of epileptic encephalopathy and supports the association between this mutation site and clinical phenotype." (PMID 39416860, 2024). "Genetic alterations in the WW domain-containing oxidoreductase (WWOX) gene cause autosomal recessive developmental and epileptic encephalopathy, characterized by the onset of refractory seizures in infants, along with severe axial hypotonia and profoundly impaired psychomotor development." (PMID 35712340, 2022). "Furthermore, the role of WWOX gene in brain development is crucial and the relationship between epileptic encephalopathy with gene mutation warrant further studies to determine the exact pathophysiology." (PMID 27495153, 2016). "The deletion partially removes WWOX coding region (intron 8–9 to 5′UTR), whose biallelic variants are known to cause a severe early-onset epileptic encephalopathy." (PMID 38459225, 2024). "However, the mechanism by which WWOX gene variants cause epileptic encephalopathy is unknown." (PMID 39416860, 2024). "There are two main neuropathological phenotypes correlated with WWOX bi-allelic pathogenic variants: SCAR12 spinocerebellar ataxia-12 (SCAR12 syndrome) and WWOX-related epileptic encephalopathy (WOREE)." (PMID 35573960, 2022).
hepatocellular carcinoma (15 papers, 2004 to 2026). A malignant tumor that arises from hepatocytes. "WWOX loss is associated with enhanced survival of a hepatoma cell line, whereas WWOX overexpression induces apoptosis and suppresses proliferation." (PMID 41007296, 2025). "Using WWOX liver-specific knockout mice, it has also been reported that inhibition of HIF1α significantly delays hepatocellular carcinoma induced by loss of WWOX expression." (PMID 33946771, 2021). "In contrast, WWOX rs73569323 SNP is negatively associated with the risk of hepatocellular carcinoma." (PMID 34948746, 2021). "In contrast, WWOX rs73569323 SNP is found to decrease the risk of hepatocellular carcinoma." (PMID 34948746, 2021). "In our previous studies, we discovered COTE1 facilitated progression of hepatocellular carcinoma via WW domain containing oxidoreductase- (WWOX-) mediated cell cycle, apoptosis, and cellular invasion modulation." (PMID 37780485, 2023). "In the hepatocellular carcinoma, toosendanin functions as WW-domain containing oxidoreductase (WWOX) agonist and thereby inhibits tumor metastasis by the inhibition of JAK2/Stat3 and Wnt/β-catenin signaling pathways." (PMID 36408249, 2022). "In the present study, we found that evodiamine, the main component of Evodia rutaecarpa, exerted an inhibitory effect on hepatocellular carcinoma in vivo and in vitro, and this activity was related to the increase of WWOX expression." (PMID 28708106, 2017). "In the present work, we found that evodiamine increased the expression of WWOX in both Mus musculus and Homo sapiens liver cancer cell lines, as well as in the tumor in Hepa1-6 hepatoma-bearing mice." (PMID 28708106, 2017). "The loss of oxidoreductase WWOX and HER2 gains could be potentially associated with NASH-induced hepatocellular carcinoma." (PMID 36587184, 2022). "Evodiamine treatment dose-dependently increased the expression of WWOX in both Mus musculus and Homo sapiens hepatocellular carcinoma cells, implying that evodiamine might activate WWOX to exert an anti-tumor activity." (PMID 28708106, 2017). "Moreover, the expressions of WWOX were dose-dependently increased in HCC cell lines as well as in Hepa1-6 hepatoma-bearing mice after the treatment with evodiamine." (PMID 28708106, 2017). "Another cancer in which the perturbation of WWOX-HIF1α interaction and its impact on carcinogenesis has been studied is hepatocellular carcinoma (HCC)." (PMID 41007296, 2025). "In the remaining analysed cancers, a higher WWOX/HIF1A expression ratio also allowed for determining the prognosis; in brain tumours and hepatocellular carcinoma, it clearly correlated with better survival." (PMID 41007296, 2025). "On the other hand, SENP2 regulates the stability of β-catenin via a WW domain-containing oxidoreductase (WWOX) and thereby regulates the growth of hepatocellular carcinoma cells." (PMID 25893082, 2015).
WOREE syndrome (15 papers, 2019 to 2026). "Our findings extend the variant spectrum of WOREE syndrome and support the critical role of the WWOX gene in neural development." (PMID 37974179, 2023). "Biallelic missense (hypomorphic) variants in the WWOX gene are associated with SCAR12, while two null alleles are associated with the WOREE syndrome." (PMID 37974179, 2023). "In conclusion, we reported a compound heterozygous deletion composed of a discontinuous deletion of intron 5 and exon 6 in one allele and an exon 6 to 8 deletion on the other allele in the WWOX gene, which causing a more severe early infantile WOREE syndrome." (PMID 37974179, 2023). "Our findings extend the mutation spectrum of the WOREE syndrome and support an important role for the WWOX gene in neural development." (PMID 37974179, 2023). "In WOREE syndrome, WWOX pathogenic variants lead to a variable loss of function of WWOX protein, which is highly conserved across species and mainly expressed in the cerebellum, brain, thyroid, hypophysis, and reproductive organs." (PMID 38161429, 2023). "Mutations in the human WWOX gene cause devastating developmental and neurological diseases in young children called WOREE syndrome and SCAR12 syndrome." (PMID 34268881, 2021). "Human germline biallelic mutations in WWOX are associated with spinocerebellar ataxia, autosomal recessive-12 (SCAR12), and WWOX-related epileptic encephalopathy (WOREE) syndrome." (PMID 41228229, 2025). "WWOX gene deficiency from bi-allelic alterations in chromosome 16q leads to autosomal recessive spinocerebellar ataxia 12 (SCAR12) and WWOX-related epileptic encephalopathy (WOREE) syndromes." (PMID 38542478, 2024). "A chromosomal microarray, choosing a quantitative method to analyze the WWOX locus, should be performed in patients with clinical features suggestive of WOREE syndrome." (PMID 38161429, 2023). "The observation of prenatal brain malformations in WOREE syndrome is consistent with animal studies showing abundant WWOX expression in the CNS of mouse embryos, suggesting an important role of the gene in CNS development." (PMID 32581702, 2020). "Together, WWOX deficiency in newborns suffer the disorder of sex differentiation (DSD), spinocerebellar ataxia (SCA), early infantile epileptic encephalopathy (EIEE), and WWOX-related epileptic encephalopathy (WOREE syndrome)." (PMID 34359949, 2021). "Importantly, germline inactivation WWOX gene has been described in humans as leading to autosomal recessive disorders such as WOREE syndrome (WWOX-related epileptic encephalopathy)." (PMID 33946771, 2021). "Germline WWOX pathogenic variantshave been associated with disorder of sex differentiation (DSD), spinocerebellarataxia (SCA), and WWOX-related epilepticencephalopathy (WOREE syndrome)." (PMID 30356099, 2019). "Moreover, WWOX germline mutations were recognized as the cause of severe developmental pathologies of the brain, such as autosomal recessive spinocerebellar ataxia 12 (SCAR12) and WWOX-related epileptic encephalopathy (WOREE syndrome)." (PMID 36271927, 2022). "Patients harboring pathogenic germline bi-allelic WWOX variants have been described with the rare devastating neurological syndromes autosomal recessive spinocerebellar ataxia 12 (SCAR12) (6 patients) and WWOX-related epileptic encephalopathy (DEE28 or WOREE syndrome) (56 patients)." (PMID 33916893, 2021). "Although WWOX was initially discovered as a putative tumor suppressor, no case report has documented the development of cancer in patients with WOREE syndrome." (PMID 41124647, 2026).
pancreatic cancer (14 papers, 2009 to 2025). "Using our pancreatic cancer model, we found that WWOX loss results in the activation of several known pathways implicated in PDAC formation, some of which have been previously linked to WWOX function, such as hypoxia, DDR, and TGFβ signaling." (PMID 36572673, 2022). "Previous studies have shown a gradual loss of WWOX expression with the progression of preneoplastic lesions in pancreatic cancer." (PMID 36572673, 2022). "Overexpression of VOPP1 has been reported in several cancers such as a glioblastoma and head and neck, lung, gastric, and pancreatic carcinomas, which are malignancies commonly affected by WWOX loss of expression." (PMID 30285739, 2018). "Recent studies have reported that WWOX polymorphism is associated with the susceptibility to several carcinomas including lung, breast, bladder, colorectal, and pancreatic cancers." (PMID 27655721, 2016). "Research indicates that site-specific promoter hypermethylation of the WWOX gene is observed in 2 out of 15 (13%) primary pancreatic adenocarcinoma patients and in 2 out of 9 (22%) pancreatic cancer cell lines." (PMID 41228229, 2025). "Research has shown that the ectopic expression of WWOX triggers apoptosis via a caspase-dependent pathway and inhibits the growth of prostate, lung, breast, cervical cancer, and pancreatic cancer both in vitro and in vivo." (PMID 41228229, 2025). "WWOX, the tumor suppressor WW domain‐containing oxidoreductase (WWOX), one of the most active fragile sites in the human genome, is commonly altered in pancreatic cancer." (PMID 40952239, 2025). "All pancreatic cancer cell lines and 40% of primary tumors exhibit a significant reduction in WWOX protein expression." (PMID 36572673, 2022). "In previous studies, WWOX was reported to be lost in pancreatic cancer cell lines, either by deletion or promoter hypermethylation." (PMID 36572673, 2022). "One study suggested that WWOX suppresses pancreatic cancer by upregulating SMAD4 signaling in Panc1 cells." (PMID 36572673, 2022). "Altogether, these findings further indicated the role of WWOX in tumor suppression in human pancreatic cancer cells." (PMID 36572673, 2022). "Our current study demonstrates that somatic WWOX loss combined with oncogenic activation (RasG12D) in the Ptf1a mouse model resulted in accelerated formation of ADM, PanINs, and pancreatic tumors." (PMID 36572673, 2022). "Overall, our findings reveal an essential role of WWOX in pancreatic cancer development and progression and underscore its role as a bona fide tumor suppressor." (PMID 36572673, 2022). "We have previously shown that WW domain-containing oxidoreductase (WWOX) has tumour-suppressing effects and that its expression is frequently reduced in pancreatic carcinoma." (PMID 19352382, 2009). "Notably, WWOX expression is significantly elevated in the pancreatic cancer cell line Hs766T following treatment with the DNA methyltransferase inhibitor 5-aza-2′-deoxycytidine." (PMID 41228229, 2025). "In addition to genomic aberrations, hypermethylation of the WWOX promoter is evident in some pancreatic cancer cell lines and in primary pancreatic adenocarcinoma cases." (PMID 36572673, 2022). "Furthermore, restoration of WWOX protein expression in pancreatic cancer cell lines induced apoptosis and suppressed tumorigenicity both in vitro and in vivo." (PMID 36572673, 2022). "Interestingly, WWOX expression levels are mostly found to be down regulated in liver and pancreatic tumours whereas they are significantly increased in colon cancer cells, as compared to normal cell counterpart." (PMID 26010871, 2015). "The tumor suppressor WW domain-containing oxidoreductase (WWOX), one of the most active fragile sites in the human genome (FRA16D), is commonly altered in pancreatic cancer." (PMID 36572673, 2022). "WWOX is a tumor suppressor gene that spans the second most common human fragile site FRA16D, and is disrupted in many tumors, including pancreatic carcinoma." (PMID 20174558, 2010).
glioblastoma (13 papers, 2013 to 2025). The most malignant astrocytic tumor (WHO grade IV). "The relative amount of protein indicated the overexpression of WWOX in T98G, DBTRG-05MG, U251MG, and U87MG glioblastoma cell lines in comparison with “CONTROL” variants." (PMID 36979157, 2023). "The change in WWOX gene expression dictates a myriad of alterations through WWOX-dependent genes that affect both glioblastoma cytoskeleton and metabolism." (PMID 34204789, 2021). "The WWOX gene is a tumor suppressor in glioblastoma and was found to modulate the cytoskeletal machinery in neural progenitor cells." (PMID 34204789, 2021). "The malignant phenotype of glioblastoma is also affected by the WWOX gene, which is lost in nearly a quarter of gliomas." (PMID 34204789, 2021). "Together with the already described glioma biomarker, RRM2, we considered PLEK2 and GCSH as a novel WWOX-dependent biomarker triad of glioblastoma, whose subsequent investigation is advisable." (PMID 34204789, 2021). "For the first time, we propose that changes in WWOX expression dictate a myriad of alterations that affect both glioblastoma cytoskeleton and metabolism, rendering new therapeutic possibilities." (PMID 34204789, 2021). "The most striking evidence of the WWOX tumor suppressor effect is the inhibition of the growth of glioblastoma cells in an extracellular matrix environment." (PMID 25051421, 2014). "The present study was conducted on the glioblastoma cell line T98G and aimed to assess the influence of WWOX upregulation on the transcriptome and phenotype of these cells." (PMID 25051421, 2014). "The aim of the present study was to assess the influence of WWOX gene upregulation on the transcriptome and phenotype of the T98G glioblastoma cell line." (PMID 25051421, 2014). "WWOX gene expression was found to be downregulated or lost in several types of cancer and this was related to the poor prognosis in tumors of the breast, liver, ovary, bladder, and kidney, as well as to glioblastoma." (PMID 36979157, 2023). "Therefore, the purpose of this study was to investigate WWOX-dependent genes in glioblastoma and indicate cytoskeleton-related processes they are involved in." (PMID 34204789, 2021). "This study is the first to evaluate the role of WWOX in cytoskeleton dynamics of glioblastoma." (PMID 34204789, 2021). "Therefore, this study aimed to investigate the role of WWOX and its collaborators in cytoskeleton dynamics of glioblastoma." (PMID 34204789, 2021). "To specify how WWOX may influence cancer cell metabolism, we decided to use the T98G glioblastoma cell line, which has a very low level of expression of endogenous WWOX to ascertain the effect an increase in WWOX expression may have on these cells." (PMID 25051421, 2014). "Expression of WWOX is either altered or lost from epigenetic modification in multiple malignant cancers, such as non-small cell lung carcinoma, hematopoietic malignancies, gastric carcinoma, pancreatic carcinoma, breast carcinoma, and glioblastoma multiforme." (PMID 23459853, 2013). "WWOX has also been found to play a significant role in glioblastoma (GBM), the most malignant brain tumor." (PMID 31543760, 2019). "Similar research is needed in the glioblastoma context since the invasion and MMP-9 expression were also reduced in our present study following WWOX overexpression." (PMID 36979157, 2023).
glioblastoma (continued). "WWOX-overexpressing cells significantly decreased the number of colonies in T98G (p < 0.0001), U251MG (p = 0.0245), and U87MG (p = 0.0275), whereas these were increased in DBTRG-05MG (p = 0.0216) glioblastoma cells." (PMID 36979157, 2023).